APOLTP (apolipoprotein lipid transfer particle homolog)
Gene: Protein-coding gene on chromosome 16 (11,359,845 to 11,527,247, reverse strand). Ensembl gene ENSG00000188897.
Subcellular location: Secreted
Gene Ontology:
Molecular function: lipid transporter activity
Biological process: lipid transport
Genetic constraint (gnomAD): Loss-of-function variants: 156 observed, 101.53 expected, observed/expected ratio (o/e) 1.54, 90% interval 1.35 to 1.75. The synonymous counts are far from expectation, so gnomAD's model fits this gene poorly and the ratio says little. Missense variants: 1,692 observed, 1,183.3 expected, observed/expected ratio (o/e) 1.43, 90% interval 1.37 to 1.49. Synonymous variants: 714 observed, 519.69 expected, observed/expected ratio (o/e) 1.37, 90% interval 1.29 to 1.46.
Homologues: Orthologues: tropical clawed frog XB6038542 (38% identical), zebrafish si:dkeyp-106c3.1 (17% identical).